ILK (integrin linked kinase)
Diseases named in the same sentence as ILK in open-access papers (continued):
Sharing a sentence is not in itself a finding about the gene and the disease.
gastric cancer (19 papers, 2005 to 2026). A primary or metastatic malignant neoplasm involving the stomach. "A kinome-wide CRISPR/Cas9 screen in FGFR2-amplified gastric cancer cell lines (e.g., KatoIII) demonstrated that loss of focal adhesion kinase (ILK) and suppression of EGFR/HER2 signaling increased sensitivity to FGFR inhibition." (PMID 41227318, 2025). "EGFR signaling regulates ILK (Integrin Linked Kinase) to increase gastric cancer cells proliferation." (PMID 26635609, 2015). "Here, we investigated the role of ILK in senescence in gastric cancer (GC) by generating ILK-depleted single-cell clonal populations from two human gastric epithelial cancer lines (MKN1 and MKN28) with different histological phenotypes." (PMID 35778385, 2022). "Through a CRISPR screen implemented in gastric cancer cell line, ILK, CSK and EGFR pathways have been identified as critical roles in the resistance to FGFR inhibitor." (PMID 35372044, 2022). "For example, in gastric cancer cells, ILK silencing inhibited drug resistance via pAkt and pErk suppression." (PMID 34163519, 2021). "Using a kinome-wide CRISPR/Cas9 screen, 20 kinases involving ILK (Integrin-linked kinase), SRC, and EGFR signaling were found to alter sensitivity to FGFR inhibition in FGFR2 amplified gastric cancer cell lines." (PMID 35582593, 2019). "Although not previously implicated in the pathogenesis of ABC-DLBCL, miR-625 has been shown to regulate invasion and metastasis in gastric cancer by targeting and regulating the expression of ILK." (PMID 25723320, 2015). "ERK1/2 mediates NF-κB activation through a mechanism involving MAPK/p90RSK/IκBα signaling; similarly, we demonstrated that this pathway was required for ILK-mediated NF-κB activation in gastric cancer cells." (PMID 25398317, 2014). "By using genetic and pharmacological approaches, we confirmed the proliferation-promoting role of ILK in vitro in gastric cancer cells." (PMID 25398317, 2014). "Although the potent mechanisms for ILK-regulated cell proliferation have been previously documented, we further investigated the molecular basis of ILK-mediated gastric cancer cell growth, which is related to NF-κB activation." (PMID 25398317, 2014). "An in vivo model of gastric cancer in mice showed the essential role of ILK in tumor growth, and increased ILK and NF-κB activity or expression is related to gastric tumorigenesis." (PMID 25398317, 2014). "Inhibiting ILK with short hairpin RNA or T315, a putative ILK inhibitor, abolished NF-κB-mediated the growth in the human gastric cancer cells AGS, SNU-1, MKN45, and GES-1." (PMID 25398317, 2014). "RNAi-based ILK silencing attenuates gastric cancer cell growth, whereas ILK overexpression is related to gastric tumorigenesis." (PMID 25398317, 2014). "Increased ILK expression is related to high-grade gastric cancer, prostate cancer, and non-small cell lung cancer, although cells in these cancers commonly harbor Ras mutations." (PMID 25398317, 2014). "A previous study showed that ILK activates NF-κB via Erk in gastric cancer cell lines." (PMID 36930690, 2023). "In gastric cancer cells, ILK knockdown could inhibit cell growth and invasion by impairing the ERK1/2/NF-κB pathway activation and F-actin assembly." (PMID 37568802, 2023). "Moreover, we demonstrated that targeting ILK increased the effectiveness of FGFR inhibition for gastric cancer with FGFR2 amplification." (PMID 31076567, 2019). "Targeting ILK with siRNA decreases gastric cancer cell invasion, proliferation, and growth through an unknown mechanism." (PMID 25398317, 2014). "miRNA-625 promotes invasion and metastasis of gastric cancer by targeting ILK." (PMID 23387986, 2013). "In parallel, CRISPR-based screens have identified regulators of FGFR, such as ILK, which modulates FGFR inhibitor sensitivity in gastric cancer." (PMID 41584352, 2026).
gastric cancer (continued). "Our laboratory has found that LPS induces ILK-dependent phosphorylation of Akt and GSK3β, as well as phosphorylation of NF-κB p65 at Ser536 and TNF-α production in gastric cancer cells." (PMID 34163519, 2021). "We observed synergistic effects on KatoIII cells as well as three additional gastric cancer cell lines with FGFR2 amplification when AZD4547 was combined with small molecular inhibitors Cpd22 and lapatinib targeting ILK and EGFR/HER2, respectively." (PMID 31076567, 2019). "Co-targetting of FGFR and ILK, an upstream receptor of GSK3β in FGFR2 amplified gastric cancer cell lines, resulted in synergistic anti-tumour responses." (PMID 35582593, 2019). "We identified the molecular basis for the regulation of ILK and its alternative role in conferring ERK1/2/NF-κB-mediated growth advantages to gastric cancer cells." (PMID 25398317, 2014). "ILK and EGFR are both the significantly depeleted genes in this screen, which means the combinational inhibition of them and FGFR can ideally boost the efficacy of the treatment to gastric cancer." (PMID 35372044, 2022). "ILK-mediated AKT phosphorylation at Ser473 was confirmed in lung adenocarcinoma A549 cells but not in gastric cancer cells." (PMID 25398317, 2014). "However, the role of ILK in cellular senescence in gastric cancer (GC) has not been previously examined." (PMID 35778385, 2022). "An increase in ILK non-canonically promotes ERK1/2/NF-κB activation and leads to the growth of gastric cancer cells." (PMID 25398317, 2014). "Using gastric cancer cells (AGS, MKN45, and SNU-1), we studied the molecular regulation of ILK and identified a non-canonical pathway of ILK-regulated ERK1/2 activation for NF-κB-mediated gastric cancer cell growth, migration, and survival promotion." (PMID 25398317, 2014). "Based on the finding that PI3K/PTEN/HSP90-regulated ILK upregulation induces non-canonical IQGAP1/Ras/ERK1/2-mediated NF-κB activation and growth advantages in gastric cancer cells, targeting this pathway may be beneficial when used in combination with other anticancer agents." (PMID 25398317, 2014).
diabetes (14 papers, 2014 to 2024). "Consistently, in this study, the STZ-induced type 2 diabetes model showed a significant decrease in cardiac ILK expression, indicating that diabetes affects ILK expression in the heart." (PMID 38543160, 2024). "HGF enhances the neo-epithelialization via the β1-integrin/ILK pathway, and its exogenous administration improves the wound healing in diabetes mellitus in mice." (PMID 34445365, 2021). "Both upregulation and downregulation of ILK expression and/or activity have been implicated in the pathogenesis of a wide variety of diseases such as diabetes, myocardial infarction, obesity or pulmonary hypertension, suggesting ILK as a molecular target and a prognostic biomarker of these diseases." (PMID 38734696, 2024). "To control for confounding factors, we used stepwise multiple logistic regression to create a multivariate model that included age, calcification degree, ILK levels, and comorbidities related to atherosclerosis and valvular calcification, such as diabetes, hypertension, and dyslipidemia." (PMID 36139812, 2022). "Since ILK or IPP is highly upregulated in multiple diseases, such as cancer, diabetes, and heart failure, our findings also open the door for developing unique therapeutic inhibitors of ILK, not as a kinase, but as a pseudokinase, by targeting at its Mg-ATP site or its binding to other proteins." (PMID 30367047, 2018). "The findings described here support the hypothesis that the HG milieu of diabetes increases TGF-β1 secretion, which increases the synthesis of ILK and α-SMA that are involved in the progression of DN." (PMID 25142208, 2014). "The findings described here support the hypothesis that the high-glucose milieu of diabetes increases TGF-β1 secretion, which increases the synthesis of ILK and α-SMA that are involved in the progression of DN." (PMID 25142208, 2014).
dilated cardiomyopathy (14 papers, 2010 to 2025). "Top significant canonical pathways included dilated cardiomyopathy signalling (−logp value = 4.82), integrin‐linked kinase (ILK) signalling (−logp value = 4.53), circadian rhythm signalling and calcium signalling." (PMID 41243421, 2025). "Mutations in ILK have been reported in human patients with dilated cardiomyopathy (DCM) and targeted ILK deletion in the murine heart causes spontaneous DCM and heart failure." (PMID 37452166, 2023). "Evidence from a previous study indicated that targeted ILK deletion caused dilated cardiomyopathy and spontaneous heart failure in murine hearts, supplementing the knowledge about the function of ILK in heart failure." (PMID 36964489, 2023). "Conditional ILK deletion in the mouse heart causes spontaneous dilated cardiomyopathy and sudden death at 6 to 12 weeks of age, suggesting an important and distinct role of ILK during vertebrate cardiac morphogenesis." (PMID 22666394, 2012). "Notably, conditional ILK deletion in the mouse heart causes spontaneous dilated cardiomyopathy (DCM) and sudden death at 6 to 12 weeks of age." (PMID 21625516, 2011). "The purpose of the present study was therefore to investigate whether overexpression of ILK can improve cardiac function of rats with doxorubicin-induced heart failure, a model of dilated cardiomyopathy, as well as to determine the mechanisms underlying its beneficial effects in this condition." (PMID 22348065, 2012). "In addition, ILK-null mutants in zebrafish are rescued by wild-type, kinase-active ILK, but not by ILK containing mutations within the kinase domain, and kinase-deficient mutants of ILK have been identified in the myocardium of patients with dilated cardiomyopathy." (PMID 20827300, 2010). "Targeted ILK ablation in the murine heart induces dilated cardiomyopathy and spontaneous heart failure." (PMID 32144627, 2021). "ILK overexpression also improves cardiac function and decreased mortality in a model of dilated cardiomyopathy." (PMID 32144627, 2021). "Knockout of the ILK gene in the murine heart induced dilated cardiomyopathy and spontaneous heart failure." (PMID 32144627, 2021). "Deletion of ILK from the murine heart results in dilated cardiomyopathy and spontaneous heart failure." (PMID 22348065, 2012). "The aim of this study is to demonstrate the therapeutic and survival benefit of cardiac ILK overexpression in a rat model of dilated cardiomyopathy." (PMID 22348065, 2012). "These included pathways such as actin cytoskeleton signaling, BAG2 signaling, calcium signaling, dilated cardiomyopathy signaling, gluconeogenesis, glycolysis, ILK signaling, integrin signaling, oxidative phosphorylation, RhoGDI signaling, and signaling by Rho Family GTPases." (PMID 37658118, 2023). "Large scale proteomics (space omics) identified two canonical protein pathways associated to muscle weakness (necroptosis, GP6 signaling/COL6) in SDM and four key pathways (Fatty acid β-oxidation, integrin-linked kinase ILK, Rho A GTPase RHO, dilated cardiomyopathy signaling) explicitly in LDM." (PMID 36835504, 2023). "These were the two SDM-associated pathways, necroptosis, GP6 signaling, and the four LDM-associated pathways, fatty acid β-oxidation, ILK, RHO, and dilated cardiomyopathy signaling that characterize metabolic SOL muscle changes in short vs. long duration mission conditions in spaceflight." (PMID 36835504, 2023). "Transfection with the ILK gene attenuated left ventricular remodeling and improved cardiac function in rats after myocardial infarction, while also improving cardiac function and decreasing mortality in a model of dilated cardiomyopathy." (PMID 32144627, 2021). "Fatty acid β-oxidation, ILK, RHOA, and dilated cardiomyopathy signaling characterize LDM exposure whereas two other pathways (necroptosis and GP6 signaling) characterize SDM exposure." (PMID 36835504, 2023).
dilated cardiomyopathy (continued). "It has been found that ILK, a mechanoreceptor protein, regulates SERCA-2a and PLN to improve the mechanical forces conduction of damaged cardiomyocyte in patients with dilated cardiomyopathy, and eventually ameliorating the myocardial systolic function." (PMID 29379038, 2018). "Utilizing failing human heart tissues (dilated cardiomyopathy, DCM), we found a 2.27-fold (p<0.001) enhanced expression of PINCH, 4 fold for α-parvin, and 10.5 fold (p<0.001) for ILK as compared to non-failing (NF) counterparts." (PMID 21625516, 2011).
myocardial infarction (14 papers, 2011 to 2024). Gross necrosis of the myocardium, as a result of interruption of the blood supply to the area, as in coronary thrombosis. "Integrin-linked kinase (ILK) attenuated ventricular remodeling and improved cardiac function in rats after myocardial infarction." (PMID 32144627, 2021). "For example, ILK gene therapy has been reported to improve cardiac remodeling and function in rats after myocardial infarction and was associated with increased angiogenesis, reduced apoptosis, and increased cardiomyocyte proliferation." (PMID 32650831, 2020). "In a model of acute myocardial infarction, we have previously demonstrated that ILK treatment reduces cardiomyocyte apoptosis both in the border and more remote zones." (PMID 22348065, 2012). "We have previously shown that ILK gene therapy can attenuate ventricular remodeling and improve cardiac function in a rat model of myocardial infarction." (PMID 22348065, 2012). "In our pervious work, overexpression of ILK after myocardial infarction can significantly induced myocardium hypertrophy and tissue angiogenesis to improve heart function." (PMID 21949693, 2011). "Previous studies have shown that ILK can induce angiogenesis, cell growth, proliferation, survival and differentiation in non-cardiac cells, whilst we have previously shown these same effects on cardiomyocytes following ILK treatment in the context of myocardial infarction." (PMID 22348065, 2012). "Interestingly, a study on myocardial infarction in mice showed that thymosin β4 (Tβ4), a monomeric G-actin protein, targets ILK-PINCH-1 leading to the activation of Akt for cardiac protection after ischemic insult." (PMID 21625516, 2011). "Together, our results support a model in which protection against myocardial infarction and DOX cardiotoxicity depends upon a functional module minimally comprised by ILK (WT and R211A) and Hsp70." (PMID 24260102, 2013).
pancreatic cancer (14 papers, 2010 to 2025). "The interaction between L1CAM-FL-ECD and integrins leads to activation of integrins and downstream phosphorylation and activation of focal adhesion kinase (FAK), proto-oncogene tyrosine-protein kinase Src, and integrin-linked kinase in pancreatic cancer." (PMID 31455004, 2019). "In this study, we report an alternative mechanism by which integrin-linked kinase (ILK) post-transcriptionally modulates the expression of MUC1-C by maintaining its protein stability in pancreatic cancer cells." (PMID 28692035, 2017). "Nevertheless, genetic knockdown or pharmacological inhibition of ILK caused depleted MUC1-C expression in IL-6-treated pancreatic cancer cells, indicating that ILK is required to sustain STAT3-induced MUC1 upregulation by maintaining its stability." (PMID 28692035, 2017). "In pancreatic cancer, snail expression correlates with that of integrin-linked kinase (ILK), a known inducer of EMT." (PMID 24281218, 2010). "Some studies have reported that the differentially expressed UGT1A gene family functions in pancreatic cancer tissues are mainly related to the glucuronylation pathway, cytokine-cytokine receptor interactions, and the ILK signaling pathway." (PMID 37056387, 2023). "Further, we found that key nodes of regulation by our confirmed hits in this interaction map were known molecules that modulate survival, EMT and drug resistance in Ras mutated pancreatic cancers, such as YAP1, SIRT1, BAG3, ILK, CDK5, HDACs or GSK3β." (PMID 30325918, 2018). "From a mechanistic perspective, the present finding, together with our recent report that ILK controls the expression of oncogenic KRAS through a regulatory loop, underscores the pivotal role of ILK in promoting pancreatic cancer progression." (PMID 28692035, 2017). "Furthermore, the ILK pathway was found to cross-talk with the KRAS pathway via a KRAS-ILK-hnRNPA1 regulatory loop in pancreatic cancer as well as in lung adenocarcinoma." (PMID 34233735, 2021). "Similarly, upregulation of the ILK pathway is found in colorectal, breast, gastric and pancreatic carcinoma." (PMID 33256002, 2020). "Cell migration and invasion have been proven to be important roles of CTEN, involving several proteins and signaling pathways, including KRAS/BRAF, Src/ROCK/SNAIL, ILK, and FAK in colorectal and pancreatic cancer, and Rho/ROCK/MLC in hepatocellular carcinoma, via DLC-1." (PMID 36851390, 2023). "From a mechanistic perspective, the unique ability of ILK to regulate MUC1-C stability, in conjunction with STAT3-activated MUC1 gene expression, upregulates MUC1-C and enables pancreatic cancer cells to interact with the tumor microenvironment to promote an aggressive phenotype." (PMID 28692035, 2017).